IL6 (interleukin 6)
Diseases named in the same sentence as IL6 in open-access papers (continued):
Sharing a sentence is not in itself a finding about the gene and the disease.
COVID-19 (continued). "In addition, patients in the acute COVID-19 phase showed a higher level of IL-6 than those with long COVID-19." (PMID 37095536, 2023). "Different chest computed tomography (CT) scoring systems have shown a prognostic value in COVID-19, but not specifically in anti-IL-6-treated patients at high risk of respiratory failure." (PMID 37218940, 2023). "Moreover, we found an association between executive function alterations and inflammatory markers in post-COVID-19 subjects (IL-6, fibrinogen)." (PMID 37189896, 2023). "The reason for this phenomenon was later explained in a review, in the early stage of COVID-19, cytokines may have a protective effect, while in the late stage, IL-6 will be cis phagocytic regulation, promoting cell growth and survival." (PMID 37483597, 2023). "Similarly, inflammatory mediators IL-6 and TNFα also contribute to myocardial remodeling and worse outcomes in COVID-19." (PMID 37568870, 2023). "Based on their findings, LSECs respond to IL-6 through differentiating into a procoagulant and proinflammatory phenotype that stimulates platelet recruitment in sinusoids and liver neutrophil aggregation, promoting COVID-19-related liver injury." (PMID 37376587, 2023). "The IL-6 elevation can be used for early recognition of severe COVID-19 complications." (PMID 37608339, 2023). "The loss of butyrate-producing anti-inflammatory bacteria (e.g., Faecalibacterium and Roseburia) as well as the upregulation of proinflammatory mediators (e.g., CRP, IL-6 and soluble IL-2 receptor (sIL2R)) was more pronounced in severe/critical COVID-19 patients than mild patients." (PMID 37205106, 2023). "In this work we found elevated proinflammatory cytokines IL-6, IL-10, IL-2 and IL-17, and importantly we noted that 12 of 20 COVID-19 severely ill patients and 13 of 20 critically ill patients had lymphopenia (lymphocyte values below 1000/ mL), which coincides with the observations of other authors." (PMID 36835858, 2023). "Studies of COVID-19 patients also showed significant increases in proinflammatory cytokines and chemokines, including IL-6, IL-1β, TNF-α, and granulocyte–macrophage colony-stimulating factor, in patients’ plasma, with much higher levels in the plasma of critically ill patients." (PMID 37628764, 2023). "IL-6 concentrations have been correlated with COVID-19 disease severity." (PMID 37546738, 2023). "Routine laboratory blood tests, including Eosinophils (EO), C-reactive protein (CRP), interleukin 6 (IL-6), Prothrombin time (PT), and lactate dehydrogenase (LDH), have been implicated in the pathogenesis of COVID-19 and are used as indicators of disease severity." (PMID 38094227, 2023). "IL-6, along with other demographic and clinical variables affected COVID-19 severity." (PMID 37960722, 2023). "IL-6 was increase in all forms of COVID-19, with a major rise in severe and critical patients." (PMID 36838284, 2023). "In addition, elevated levels of the proinflammatory cytokines IL-6 and TNF-α in COVID-19 patients cause damage to the lymphatic system, resulting in immunosuppression, which contributes to the progression of TB." (PMID 38162574, 2023). "Interestingly, two adipocytokines, IL-6 and tumor necrosis factor-alpha (TNFα), are related to COVID-19 severity and patients’ death." (PMID 38110483, 2023). "In the case of patients with severe COVID-19, the high levels of T cells may be stimulated by cytokines other than IL-6." (PMID 38137381, 2023). "Two different IL-6 concentrations were employed: a) 20 pg/mL (similar to the maximum plasma level detected in the total COVID-19 patients recruited; Media= 22,88 pg/mL), and b) 20 ng/mL (the plasmatic concentration in severe-to-critical COVID-19 disease, recommended for tocilizumab treatment)." (PMID 37818368, 2023). "However, the concept of CCS and the critical role of IL-6 is not limited to complications of COVID-19 but has been observed in diverse infections and immune-mediated diseases." (PMID 37951972, 2023).
COVID-19 (continued). "Interestingly, IL-6 blockade in COVID-19 plasma with tocilizumab significantly reduced the high levels of TF+-platelet MVs and PNAs when compared to control plasma." (PMID 37275917, 2023). "In patients with COVID-19, serum IL-6 levels were elevated in those with AKI." (PMID 38203482, 2023). "Indeed, IL-6 testing in COVID-19 patients has played a pivotal role in predicting poor prognoses and a higher risk of developing respiratory failure." (PMID 37214473, 2023). "In addition, several of the elevated inflammatory markers in patients with COVID-19, e.g., interleukin-6 (IL-6), tumor necrosis factor (TNF), and ferritin have been found to correlate positively with pCRP levels." (PMID 37724104, 2023). "In general, infection, which in the case of COVID-19 may be prevented by vaccination, may be connected with elevated levels of cytokines in the amniotic fluid: interleukin-1β (IL-1β), interleukin-6 (IL-6), and prostaglandins, such as PGE2 and PGE2a." (PMID 37629228, 2023). "In severe COVID-19 cases, IL-6 levels were 2.9 times higher than in cases with less severe disease." (PMID 36829806, 2023). "Exploratory studies have suggested that interleukin-6 (IL-6) is related to COVID-19; however, the correlation between IL-6 and long COVID-19 is unknown." (PMID 37095536, 2023). "Along with an increase in the expression levels of HLA-DR and PD-1, and elevated IL-6 serum concentration, an increase in the CD16+ cell proportion among CD56− T cells may be considered the factor associated with increased COVID-19-mediated mortality." (PMID 37240393, 2023). "The understanding of the functional basis of the association between the IL6 C allele with COVID-19 severity is still not clear." (PMID 37243282, 2023). "Additional evidence of the relevance of IL-6 and their receptors in COVID-19 is the reporting of successful therapeutical use of monoclonal antibodies anti-IL-6 receptors in COVID-19, whose use has been proven to be effective in a number of autoimmune diseases." (PMID 37243282, 2023). "It is shown that COVID-19 increases the production of IL-6 as well as ATX, hence anti-ATX therapy could be an effective treatment for COVID-19." (PMID 37089604, 2023). "Targeting neutrophil-related cytokines such as IL-1β, IL-1R, IL-6, and IL-17 could be a valuable strategy to enhance the clinical efficacy of COVID-19." (PMID 37533131, 2023). "The IL-6/JAK/STAT-3 axis potently potentiates inflammatory responses and may cause the decrease of lymphocytes in COVID-19." (PMID 37495990, 2023). "Furthermore, we found that patients with higher CURB-65 scores before treatment had larger baseline concentrations of IL-6, which has been highlighted to play a key role in the cytokine storm characterizing COVID-19 patients." (PMID 36769445, 2023). "Several studies showed that IL-6 serum levels are increased in patients with COVID-19." (PMID 37569398, 2023). "A higher IL-6 serum concentration (>100 pg/mL) was predictive of TCZ’s effectiveness in COVID-19." (PMID 36983429, 2023). "A recent study has also showed that aging can alter several cytokines expression during COVID-19; in particular, hospitalized COVID-19 with > 70 years (n = 23) were characterized by increased serum IL-6 levels and decreased serum IFNγ levels, compared hospitalized COVID-19 with < 60 years (n = 26)." (PMID 36941580, 2023). "Correlation of serum IL-6 levels with neutrophil–lymphocyte ratio (NLR) values in COVID-19." (PMID 38099004, 2023). "Moreover, the prognostic value of chest CT scores and the laboratory findings in COVID-19 patients specifically treated with anti-IL-6 drugs have been assessed." (PMID 37218940, 2023). "detected an inverse relationship between levels of SNa and IL-6, in a cohort of COVID-19 patients." (PMID 37560297, 2023). "IL-6 has been considered a pivotal mediator in patients with COVID-19." (PMID 38005844, 2023).
COVID-19 (continued). "Interestingly, post- COVID-19 patients of our study were mostly healthy and reported very few debilitating symptoms, demonstrating lower IL-6 levels." (PMID 37753077, 2023). "Our findings suggested that lower hemoglobin levels may be attributed to higher levels of IL-6, which requires further study in COVID-19 patients." (PMID 36747045, 2023). "Therefore, we aimed to describe and classify immune responses especially according to IL-6 response, among patients with critical COVID-19." (PMID 37081872, 2023). "Furthermore, an elevation in levels of proinflammatory cytokines such as IL-6, serum ferritin, and CRP was observed, with IL-6 serving as a reliable predictor of COVID-19 severity and progression." (PMID 37515156, 2023). "Consequently, patients with severe COVID-19 have considerably higher blood levels of IL-2, IL-6, TNF-α, IL-1, IL-10, IFN-γ, IL-8/CXCL8, and CXCL10/IP-10 during the cytokine storm, potentially because of NF-κB via selective activation." (PMID 36851766, 2023). "In the present research, we first observed, in line with the literature, that the SARS-CoV-2 S1 spike surface protein is sufficient alone to activate the production of key COVID-19 pro-inflammatory cytokines (IL-1β, IL-6, and IL-8) in alveolar A549 cells, a major COVID-19 cell-type target." (PMID 37834316, 2023). "This pathogenic effect appears to be mediated by the decrease in uPAR expression in the specific lung cells of COVID-19 patients, which may lead to pro-fibrogenic accumulation of inactive uPA followed by IL-6 and ACE2 upregulation and EMT induction." (PMID 36674896, 2023). "In addition, TGFβ1, TGFβ3, IL-10, and IL-6 were prognostic makers for the early phase of COVID-19 severity, consistent with previous reports." (PMID 37569646, 2023). "By obtaining reliable results, it may lead to the standardization of measurement and reporting of SAA and IL-6 levels in patients with COVID-19 and CKD." (PMID 38203482, 2023). "IL-6 is another important early phase mediator that has been associated with negative prognosis in COVID-19 patients and was suggested as a possible therapeutic target." (PMID 37283766, 2023). "IL-6 was significantly increased in patients with infiltrate above the median compared to infiltrate below the median both in COVID-19 (p < 0.001, AUC = 0.78) and in non-COVID-19 (p < 0.05, AUC = 0.81)." (PMID 37733154, 2023). "In our study, IL6 was highly expressed in symptomatic COVID-19 patients with myocardial injury." (PMID 37564653, 2023). "This study suggests a mean value of IL-6 estimated at 20.92 pg/ml for long COVID-19." (PMID 37095536, 2023). "Increased levels of cytokines and chemokines, particularly IL-6, IL-8, and tumor necrosis factor, along with lymphopenia and immune cell infiltration in affected organs, are known to contribute to the severity of COVID-19 and the accompanying hyper-inflammatory responses." (PMID 38136554, 2023). "According to the study reported by Gao’s group, clinical laboratory data with an IL-6 level over 24.3 pg/mL could predict the severity of COVID-19 with a sensitivity and specificity of 73.3% and 89.3%, respectively." (PMID 36679421, 2023). "In the present study that evaluated inflammatory and coagulation biomarkers that may qualify as predictors for COVID-19 severity, we showed for the first time that IL-6 can predict severe cases of COVID-19 in patients with diabetes." (PMID 37834356, 2023). "Furthermore, a decrease in IL-6 mRNA expression observed signifies the reduction of inflammatory responses and gradual recovery of COVID-19." (PMID 36482706, 2023). "Elucidating mechanisms underlying COVID-19-induced monocyte reprogramming and developing interventions targeting key inflammatory regulators like IL-6 may mitigate the sustained inflammatory burden imposed by the aberrant trained immunity post-COVID-19." (PMID 38090572, 2023).
COVID-19 (continued). "Moreover, the literature-based pathway analysis uncovered a set of specific genes, such as CALCA, ACE, SIRT1, TNF, IL6, CCL2, and others, that were found to mediate the association between OA and COVID-19." (PMID 38020136, 2023). "Inhibition of the cytokine interleukin 6 (IL-6) using drugs such as tocilizumab, which bind to the IL-6 receptor, has been shown to reduce mortality in critically unwell patients with Coronavirus Disease 2019 (COVID-19)." (PMID 36716318, 2023). "Antiviral medications such as remdesivir, and anti-inflammatory regimens such as corticosteroids, interleukin-6 (IL-6) inhibitors, and Janus kinase inhibitors have also been reported to improve clinical outcomes in hospitalized COVID-19 patients in specific subgroups." (PMID 36817416, 2023). "It is important to note that while targeting the IL-6 pathway has shown clinical benefit in acute COVID-19, and this pathway remains aberrant in long COVID, evidence in favor of biological immunomodulatory therapies such as tocilizumab is limited to a case report." (PMID 36969241, 2023). "In a cohort study of 50 patients, severe COVID-19 was associated with impaired function of monocytes and dysregulation of type 1 interferon (IFN-1) which can lead to a higher viral load and dysregulated TNF-alpha and IL-6 systemic response." (PMID 37593250, 2023). "In vitro, IL-6 stimulation of PBMCs from COVID-19 patients diminished the NT levels on CD8 T-cells." (PMID 37818368, 2023). "However, a study claimed that CCL5 levels in the peripheral blood of severe COVID-19 patients were greater than IL-6 levels." (PMID 37153613, 2023). "This electrolyte disorder is thought to be associated with excess serum levels of interleukin-6 (IL-6) during COVID-19, which stimulate the HPA axis to induce the non-osmotic release of vasopressin." (PMID 36838326, 2023). "It is functionally characterized by elevated concentrations of pro-inflammatory cytokines such as IL-1β and IL-6, suggesting that host immune dysregulation (i.e., cytokine storm) might be one crucial determinant of critical clinical courses of COVID-19." (PMID 37834869, 2023). "Therefore, measuring the levels of IL-6, IL-12p70, CRP, and D-dimer at presentation can predict the risk of disease progression in COVID-19 patients." (PMID 37228441, 2023). "Different researchers have reported that COVID-19 patients show increased levels of pro-inflammatory cytokines, such as IL-6 and IL-1β, indicating that their modulation might affect patients’ outcomes." (PMID 37986089, 2023). "Anti-IL-6 agents have been proposed as one of the promising treatment regimens for COVID-19." (PMID 37384095, 2023). "IL-6, a proinflammatory cytokine, not only stimulates the release of other cytokines, but also activates immune cells, playing an important role in the systemic inflammation which is common in severe COVID-19 cases." (PMID 37628963, 2023). "However, recent studies have found that the IL-6 level in patients with COVID-19 is significantly lower than that in patients with sepsis, cytokine release syndrome, and hyperinflammatory ARDS." (PMID 37310657, 2023). "In the patients with COVID-19, the serum levels of IL-6 were elevated in those with AKI." (PMID 36983566, 2023). "Группы среднетяжелого и тяжелого течения COVID-19 достоверно различались по возрасту, уровням глюкозы крови, воспалительных маркеров: лейкоцитов, нейтрофилов, IL-6, D-димера, C-реактивного белка, ферритина и активности печеночных ферментов, которые коррелировали с тяжестью течения заболевания." (PMID 37694864, 2023). "Moreover, one study showed a positive correlation between gal-1; levels of pro-inflammatory cytokines such as Interleukin-1 beta (IL-1β), IL-6, and IL-23; and COVID-19 severity, suggesting that gal-1 acts as an alarmin." (PMID 37475853, 2023).
COVID-19 (continued). "In this study, IL-6 was significantly associated with the presence of GGO and CT scores in all participants with COVID-19, which agrees with previous studies demonstrating a significant predictive value of IL-6 in relation to CT scores for the prognosis of COVID-19." (PMID 37376606, 2023). "Secondly, elevated cortisol levels in COVID-19 patients could be attributed to proinflammatory cytokine IL-6." (PMID 38153951, 2023). "Our predictive models using the combination of Charlson Comorbidity Index, sex, procalcitonin, systemic TLR3 expression and IL-6 and IL-8 in BAL were able to describe a broad range of clinically relevant outcomes in patients with severe COVID-19-associated ARDS." (PMID 36631778, 2023). "We perhaps offer a strategy for identifying potential SNPs as prognostic markers with a particular attention to concurrent pandemic waves, serum IL-6 levels, clinical criteria, laboratory investigations, and treatment response among COVID-19 Egyptian population." (PMID 38155729, 2023). "An interesting observation is that 80% of septic patients have hypophosphatemia associated with elevated concentrations of inflammatory cytokines such as tumor necrosis factor (TNF) alpha and interleukin (IL)-6 and other inflammatory cytokines included in cytokine storm in COVID-19." (PMID 37568451, 2023). "In COVID-19, interleukin-6 level is elevated, and due to its mediating role in the lung and destruction of pulmonary alveoli, side effects such as drop in blood oxygen saturation level and coughing are expected, which is consistent with the results of the present study." (PMID 37692307, 2023). "Increases in metabolic markers of oxidative stress (methionine sulfoxide, cystine), proteolysis, and renal clearance dysfunction (creatine, creatinine, polyamines) were correlated with concentrations of IL6 and renal failure (another severe outcome of COVID-19)." (PMID 40729168, 2023). "However, DOAC can interact with anti-IL-6 (tocilizumab) and antivirals (lopinavir, ritonavir, or darunavir), which are often used in the treatment of COVID-19." (PMID 37092518, 2023). "In addition, Tocilizumab, which antagonises IL-6 function by targeting IL-6R, has been shown to beneficially affect survival and clinical outcomes in the treatment of COVID-19 patients with severe pneumonia." (PMID 37513775, 2023). "Moreover, the serum concentrations of IL-6 in the COVID-19 patient group were considerably higher than those of patients in the control group." (PMID 37240319, 2023). "A high incidence of lymphopenia, ranging from 67–75%, has been consistently reported among COVID-19 patients who have a severe illness; it may correlate with an increased quantity of cytokines such as IL-6, IL-10 or TNF (tumor necrosis factor)." (PMID 37754237, 2023). "In addition, MAPKs contribute to a decrease in lymphocyte counts, including lymphocyte necrosis and NK and T-cell exhaustion promoted by IL-6, which is commonly observed in COVID-19 patients." (PMID 37817178, 2023). "As a result, their findings imply that repeated measurements of circulating IL-6 levels may be crucial for detecting illness development in COVID-19-infected individuals." (PMID 37504277, 2023). "Moreover, IgG4 levels were correlated with IL-6 levels, a known determinant of COVID-19-related mortality." (PMID 37243095, 2023). "In particular, PC1 reflected the known hyper-inflammatory phenotype of COVID-19 (with greatest contributions from IL-2, IL-6, IP-10, TNF-α, IL-10, IL-33 and IL-1β) which was independently associated with severe disease, requirement for invasive mechanical ventilation and mortality." (PMID 37063871, 2023). "We describe the tyrosine-protein kinase receptor UFO as a predictor for IL-6 rise, underpinning the notion that this protein may warrant further attention as an early predictor of hyperinflammation in COVID-19." (PMID 37834869, 2023).